EGFR (epidermal growth factor receptor)
Diseases named in the same sentence as EGFR in open-access papers (continued):
Sharing a sentence is not in itself a finding about the gene and the disease.
tumor (continued). "We attempted to resolve these challenges by coating the MNPs with the tumor-targeting element cetuximab, a chimeric mouse–human monoclonal antibody that binds with high affinity to the anti-epidermal growth factor receptor (EGFR), which is expressed at high levels by various epithelial tumors." (PMID 28774062, 2016). "Triple negative tumours are known to be a heterogeneous group with a significant proportion displaying the basal-like phenotype; with overexpression of cytokeratin 5/6(CK) and epidermal growth factor receptor (EGFR) proteins." (PMID 27463681, 2016). "Furthermore, we showed that EGFR amplification was associated with ER-negative status, HER2-positive status and large tumor size (T4)." (PMID 27765917, 2016). "In addition, EGFR expression was evidently correlated with tumor size, differentiation status, hepatic metastasis and TNM stage." (PMID 27729020, 2016). "In addition, interaction of HA and CD44 promotes EGFR-mediated pathways, consequently leading to tumor cell growth, tumor cell migration, and chemotherapy resistance in solid cancers." (PMID 27200096, 2016). "Activation of EGFR downstream signaling pathways leads to increased proliferation and tumorigenesis, and stimulates angiogenesis via up-regulation of pro-angiogenic molecules in the tumor cells." (PMID 27118928, 2016). "Thus, the blockade of EGFR by inhibitors like Gefitinib significantly inhibits the tumor cell proliferation; while despite the promising clinical efficacy of these inhibitors, most responders eventually obtained resistance." (PMID 28036020, 2016). "This novel somatic EGFR mutation would not have been called somatic with high confidence if tumor-only sequencing were performed using cancer panels." (PMID 27245685, 2016). "The second observation was that at both baseline and at 3 months after starting treatment almost all CTCs expressed PD-L1, irrespective of mutational status of EGFR, of the tumor histology and history of smoking." (PMID 27553175, 2016). "Furthermore, cetuximab -activated NK cells have been shown to exert an indirect anti-tumor effect by promoting tumor antigen-anti-EGFR-specific T cells." (PMID 27519478, 2016). "Chronic inflammation may be an important process during the carcinogenesis of PeCa because it shares the activation of COX-2, PGE2 and EGFR with most of the other SCC tumor phenotypes." (PMID 27351128, 2016). "Similar to EGFR, Ki-67 overexpression is also suggestive of high tumor grade and poor prognosis." (PMID 27870887, 2016). "EGFR is an erbB family receptor tyrosine kinase expressed by a wide variety of tumor types." (PMID 27669306, 2016). "Firstly, while the patients were not selected on the basis of tumor mutation, the study population is biased towards an excess of EGFR mutations for a white population." (PMID 28027313, 2016). "Taken together, the data obtained here suggest that Dsg2 may play a significant role in tumor development by positively regulating EGFR level and signaling through a c-Src and Cav1 dependent manner." (PMID 26918609, 2016). "Thus, mAb04-MICA is a promising new approach for NK cell-based immunotherapy for malignancy and the strategy of treatment with MICA fused antibody can be further applied to other tumor specific markers such as Her2 and EGFR." (PMID 26909862, 2016). "EGFR-TKIs have been researched and developed as effective targeted anti-tumor drugs for NSCLC." (PMID 27893423, 2016). "Unfortunately, anti-ErbB3 antibodies may not result to be highly efficacious as single agents, because of tumor cells ability to escape from ErbB3 inhibition by activation of EGFR and/or ErbB2." (PMID 26862736, 2016).
tumor (continued). "Most SCCHN tumours overexpress the epidermal growth factor receptor (EGFR)." (PMID 26927178, 2016). "Finally, we examined the function of miR-218-5p in vivo and revealed that miR-218-5p exerts an anti-tumor effect by negatively regulating EGFR in a xenograft mouse model." (PMID 27057632, 2016). "Furthermore, our results demonstrated that CPEB3 is a newly discovered tumor suppressor that acts via the EGFR pathway." (PMID 26497556, 2016). "Furthermore, univariate analysis showed that gender (male), ECOG-PS ≥ 2, current or former smokers, tumor stage IV, wild-type EGFR status, neutrophilia and NLR ≥ 3.7 were significantly associated with worst PFS." (PMID 27029035, 2016). "In this study, we show that GPRC5A functions as a tumour suppressor to prevent IR-induced lung tumorigenesis, which involves GPRC5A at ER to suppress synthesis for a group of membrane-associated proteins and EGFR is the most important among them." (PMID 27273304, 2016). "Nimotuzumab thus may have an advantage for specifically targeting tumor cells with EGFR overexpression while sparing normal cells." (PMID 26778701, 2016). "In this work, we studied EGFR protein expression, gene mutations and gene copy number in a large series of BOTs, to investigate whether EGFR plays a role in the pathogenesis of these tumours." (PMID 26870997, 2016). "One study has shown that miR-146a-5p was downregulated in NSCLC cells (H358, H1650 and H1975) compared with non-tumor tissues and could inhibit cell growth and cell migration, as well as induce apoptosis by targeting the EGFR gene." (PMID 27494902, 2016). "Overall, our results suggest that NeuGcGM3 and EGFR may coordinately contribute to the tumor cell biology and that therapeutic combinations against these two targets might be a valid strategy to explore." (PMID 27449755, 2016). "Resistant clones with acquired RAS mutations may arise from a small subpopulation present within the original tumor before anti-EGFR therapy or as a consequence of continued mutagenesis over the course of targeted treatment." (PMID 27699178, 2016). "The expression of EGF/EGFR was correlated with tumor proliferation, invasion, and metastasis." (PMID 27788491, 2016). "Using CD69 surface expression to measure effector cell activation, we also observed that tumor cells with EGFR expression can activate EGFR-CAR-transduced NK-92 cells, with higher activation when MDA-MB-231 and MDA-MB-468 cells were used than when MCF-7 cells were used." (PMID 27050072, 2016). "Sixth, although ALK-positive patients were more likely to have a small tumor compared to EGFR-positive patients, this may be because of indolent nature of EGFR-positive tumors." (PMID 27518729, 2016). "We have previously shown that activation of the epidermal growth factor receptor (EGFR) is one of the mechanisms leading to the invasive, non-angiogenic tumour growth, while EGFRvIII expression appears to be associated with angiogenesis." (PMID 27049916, 2016). "Aberrant activation of EGFR in neural and glial progenitor cells, either via genetic manipulations or by treatment with exogenous ligand, induces aberrant proliferation of cells with glial features, and can lead to the formation of tumor-like lesions." (PMID 27738329, 2016).
tumor (continued). "To determine whether miR‐134 exerts its tumour suppressive functions through down‐regulation of EGFR, we first performed RNAi experiments to determine whether EGFR knockdown would mimic the phenotype of miR‐134 overexpression." (PMID 27241841, 2016). "Additionally, exposure of tumor cells to ionizing radiation can activate EGFR independently from ligands, contributing to tumor radioresistance." (PMID 27245053, 2016). "Furthermore, if PIK3CA mutation(s) caused resistance to EGFR TKI, the cancer cells with PIK3CA mutation would proliferates with tumor progression; therefore the population of PIK3CA mutant cells would increase and not be in low percentage mosaicism." (PMID 27734950, 2016). "In one case the NGS and the Therascreen revealed in the plasma the EGFR exon 19 deletion but not the p.T790M mutation that was identified in the tumor tissue (case L2)." (PMID 27448974, 2016). "Hence the identified ETSP from expression of EFEMP1 variant construct E5 would give stronger tumor suppression than the parental EFEMP1 in TMC by targeting EGFR and angiogenesis, and also would gain a new tumor-suppression function by targeting NOTCH." (PMID 27713911, 2016). "EGF through EGFR/ERBB1 activates various downstream signaling pathways which in turn trigger other transcription factors and co-activators that can affect the proliferation of tumor cells." (PMID 27564112, 2016). "In this context, several studies indicate that sEGFRs could regulate the EGFR signaling in normal and tumor tissues." (PMID 27104520, 2016). "Surprisingly, zoledronic acid and cisplatin did not decrease the weight of H1650 xenograft tumor expressing activating EGFR-mutation." (PMID 27780929, 2016). "Cytofluorimetry analyses on EGFR+ and EGFR− tumor cells confirmed the binding specificity." (PMID 26575422, 2016). "In addition, for one thing, ginsenoside Rg3 deactivates the EGFR/MAPK pathway to inhibit tumor cell proliferation." (PMID 27655708, 2016). "None of the tumor tissue samples of all 46 patients showed evidence of mutations in the cetuximab-interacting EGFR ectodomain or KRAS/NRAS." (PMID 27119512, 2016). "Furthermore, tumour uptake of the most recent iteration of irreversible EGFR imaging agents, [18F]afatinib, was sensitive to modulation by the ABCB1-specific inhibitor, tariquidar." (PMID 27552105, 2016). "Therefore, we conducted this study to prospectively investigate an association between cytologic tumor markers and FDG uptake with EGFR mutation status in NSCLC." (PMID 26979333, 2016). "In this study, EGFR inhibition has been explored both in vitro and in vivo with xenografts of EGFR-mutated NSCLC cells, in terms of its ability to modulate epithelial versus mesenchymal features and to improve tumor sensitivity to immune-mediated attack." (PMID 27685624, 2016). "All MDA-MB-468 tumours were detected reliably by in vivo SPECT scans 45 min after administration of 17 pmol anti-EGFR nanobody 99mTc-D10 as shown by signals present in the tumour and very low background signals resulting in a tumour to tissue (area of the contra lateral side) ratio of 42.8 ± 27.0." (PMID 26912069, 2016). "In addition, we found that DFS and OS significantly associated with clinical stage, tumor size, regional LN metastasis, adjuvant treatment, CEA, and Cyfra21-1 in the EGFR wild-type adenocarcinoma patients." (PMID 27072585, 2016). "Moreover, MP predominant subtypes are more likely to occur with EGFR-mut tumours in Chinese lung AC patients." (PMID 27046167, 2016). "Interestingly, inhibition of AKT signaling appears to activate some RTKs via de-repression of RTK expression and increased RTK phosphorylation, including that for EGFR in some tumor models." (PMID 27484095, 2016).
tumor (continued). "Solid or plate patterns exhibited varied EGFR statuses in different tumour masses." (PMID 27046167, 2016). "On the other hand, administration of Ad-anti-EGFR could produce a bioactive anti-EGFR antibody that suppressed tumor growth in mice." (PMID 27058423, 2016). "Although either downregulation of EGFR and ErbB2 or increased ErbB3 expression upon treatment with HDACi have been reported before in tumor cells and particularly in NSCLC cell lines, to our knowledge this is the first study reporting these effects in primary cultures." (PMID 26862736, 2016). "The average durations of DFS and OS in patients with high level circulating CK7, ELF3, EGFR, and EphB4 mRNAs (tumor PBMCs vs. positive control: >2-fold) were significantly shorter than those of patients with normal or downregulation of the four mRNAs in the PBMCs." (PMID 27827952, 2016). "Clinically, this could translate into smaller tumour shrinkage and earlier progression on anti-EGFR treatment in patients." (PMID 27929064, 2016). "Finally, we show that the early adaptive drug-resistant EGFR-mutant tumor cells under reprogrammed transcriptomic/metabolomics profiles can be secondarily targetable in principle, and are vulnerable to TGFβ2 inhibition, and glutamine-depletion." (PMID 27852038, 2016). "In addition, Pexa-Vec replication is stimulated by EGFR/Ras signaling and type-I interferon resistance, giving the virus both relative selectivity for tumor cells and the ability to replicate in tumors with diverse genetic alterations." (PMID 27669306, 2016). "In summary, our study provides new insight both into the immediate-early therapeutic response to EGFR TKIs and into dynamic changes transpiring in the immune microenvironment during that time, phenomena which may mediate the tumor response." (PMID 27494838, 2016). "Interestingly, treatment of tumor cells with EGFR tyrosine kinase inhibitors (EGFR-TKI) was shown to upregulate HLA-DR expression on tumor cells and enhance recognition by EGFR875-889-specific CD4 T cells." (PMID 27833557, 2016). "These include RB1 and EGFR, the top-scoring tumor suppressor and oncogene, respectively." (PMID 27321817, 2016). "Furthermore, fluorescence immunohistochemistry experiments confirmed that our constructs can distinguish between healthy and TNBC tumor tissues, because the latter express high levels of EGFR, EpCAM or CSPG4." (PMID 27448975, 2016). "Previous studies of EGFR mutation detection in plasma have shown similar results, with some plasma samples resulting positive in patients with the tumor tissue negative for EGFR mutations." (PMID 27448974, 2016). "In addition to inhibition of tumor growth signaling, inhibition of VEGF signaling is also essential to overcome drug resistance in tumors harboring EGFR-TKI resistance mutation." (PMID 27655708, 2016). "Analyses of EGFR and KRAS mutations were successfully performed in 170/174 (97.7%) primary tumours." (PMID 26844548, 2016). "Moreover, EGF-conjugated HAOA-coated nanoparticles did not markedly decrease HaCaT cell viability, showing high biocompatibility with healthy tissues, and were able to enter the EGFR-overexpressing tumor cell line A549, by different internalization mechanisms." (PMID 27788212, 2016). "EGFR variant III is a tumor specific mutation that is widely expressed in GBM and other neoplasms." (PMID 27833557, 2016). "The tumor size of miR‐133a‐MB injection was smaller than that of EGFR siRNA‐MB injection." (PMID 27465833, 2016). "However, several studies indicated that EGFR expression represents a good prognostic parameter, even if there is heterogeneity mainly due to IHC scoring system and tumor site variability." (PMID 27556186, 2016).
tumor (continued). "Interestingly, we recently found that recombinant human PEPD inhibits tumor growth by targeting epidermal growth factor receptor (EGFR), also known as ERBB1, and its family member ERBB2." (PMID 27248165, 2016). "We also provided evidences that the mechanism underlying the synergistic interaction between the two classes of agents is related to the downregulation of EGFR and ErBB2 and to the differential modulation of ErbB3 based on tumor cell phenotype, epithelial vs mesenchymal, induced by the HDACis." (PMID 26862736, 2016). "Combinatorial therapies including ErbB3 targeting may ameliorate tumor responses to anti-EGFR therapies." (PMID 27609096, 2016). "Therefore, differences in 89Zr-imgatuzumab uptake in A549 and H441 are most likely explained by the lower EGFR expression based upon EGFR histoscore, combined with lower tumor cell density on H&E in A549." (PMID 27602494, 2016). "Expression of EGFR has been documented in human and canine OSA, and correlated with a worse prognosis, indicating that EGFR may play a role in OSA tumor biology and therefore EGFR pathway inhibition could represent a viable treatment option for OSA." (PMID 27245053, 2016). "In the present study, there is a strong negative correlation between primary tumor size and EGFR mutations." (PMID 27472739, 2016). "Though rebiopsies have been recommended to confirm EGFR mutation status, it is not always possible to obtain them because of the tumor size and the sites of primary or metastatic tumors." (PMID 27478396, 2016). "Furthermore, PD-1 blockade-induced tumour reduction and significantly increased OS in EGFR-mutant mouse models." (PMID 27433281, 2016). "EGFR inhibitors can inhibit the growth and proliferation of tumor cells." (PMID 27788491, 2016). "In contrast, tumor size was the only factor significantly correlated with OS in the EGFR-positive subgroup (HR > 2.0, p < 0.001 for both univariate analysis and multivariate analysis), and larger tumor size clearly had the highest HR (3.27) of all the prognostic factors evaluated." (PMID 27399694, 2016). "EGFR and HER2 mutation prevalence varies according to patient/tumor selection criteria." (PMID 26689995, 2016). "Even though ALK translocations are generally mutually exclusive compared to EGFR and/or KRAS mutations, more recently the complexity of clonality, the resistance mechanisms, and the selective pressure of antiblastic treatments on tumour growth have made this principle more debatable." (PMID 27433281, 2016). "sEGFR levels in A431 tumor-bearing mice were 837 ± 71 ng/mL plasma, corresponding to ∼2.5 sEGFR for each 89Zr-imgatuzumab molecule in circulation for the 10 μg tracer dose, reflecting a high degree of competition of sEGFR with tumor-bound EGFR." (PMID 27602494, 2016). "The tumor was negative for epidermal growth factor receptor mutation but positive for the echinoderm microtubule-associated protein-like 4-anaplastic lymphoma kinase (EML4-ALK) fusion oncogene according to fluorescence in situ hybridization." (PMID 26964537, 2016). "Moreover, FeDC-E NPs inhibited phosphorylation of the EGFR as well as the EGFR–ERK–NF-κB signaling pathways of the EGFR overexpressing cells along with the expression of the downstream tumor promoting proteins MMP-9 and XIAP." (PMID 27833124, 2016). "Total (membranous and cytoplasmic) EGFR in excised sections increased with tumor growth." (PMID 27388754, 2016). "We also found that ALK-positive patients tended to have smaller tumors (≤ 3 cm) compared to those in EGFR-positive patients, suggesting that genomic state could influence the tumor size." (PMID 27518729, 2016). "When tumour location was considered as a dichotomous variable, EGFR gene amplification was still more common in proximally located tumours (distal oesophagus/GOJ/cardia versus gastric corpus/antrum/pylorus; (Fisher’s exact test, p = 0.016); OR 2.64, 95 % CI: 1.22–5.73)." (PMID 27387915, 2016).